GSN (gelsolin)
Diseases named in the same sentence as GSN in open-access papers (continued):
Sharing a sentence is not in itself a finding about the gene and the disease.
colon carcinoma (14 papers, 2003 to 2025). "In glioblastoma, lung, breast, head and neck, gastric, and colon cancers, gelsolin has an anti-tumor function, and its downregulation correlates with poor patient prognosis." (PMID 41006687, 2025). "The upregulated expression of GSN was also reported in human colon cancer cells that led to an enhanced capacity for cell migration." (PMID 37958747, 2023). "In this study, we provide evidence that the expression of gelsolin promotes invasion via mechanisms that involve an increase in intracellular O2.- in HCT116 colon cancer cells." (PMID 27391159, 2016). "We further observed reduction in invasion and intracellular O2.- levels in colon cancer cells, as a consequence of gelsolin knockdown using two different siRNAs." (PMID 27391159, 2016). "We have previously shown that increased gelsolin expression promotes colon cancer cell invasion through its involvement in the secretion and increased activiy of uPA." (PMID 27391159, 2016). "Herein, we show that increased gelsolin enhances the invasive capacity of colon cancer cells, and this is mediated via gelsolin's effects in elevating intracellular superoxide (O2.-) levels." (PMID 27391159, 2016). "Recently we reported that gelsolin expression was increased in the liver metastases of a subset of colon cancer patients." (PMID 27058427, 2016). "We have previously reported that gelsolin overexpression enhances the production and secretion of uPA, thereby promoting invasion in colon cancer cells." (PMID 27391159, 2016). "The results indicating the involvement of GSN-A in the invasion of A375 cells align with previous observations that show an increase in the level of secretory GSN in colon cancer cells forming distant metastases in patients with colon cancer, and with other types of tumors." (PMID 40597347, 2025). "Similarly, highly expressed gelsolin significantly inhibited invasion and metastasis in human colon carcinoma (CC) cells in vitro." (PMID 37719007, 2023). "As reactive oxygen species (ROS) have been shown to promote cancer cell invasion, we investigated on the hypothesis that gelsolin-induced changes in ROS levels may mediate the invasive capacity of colon cancer cells." (PMID 27391159, 2016). "Thus, our findings provide a novel mechanism by which gelsolin mediates colon cancer cell invasion via modulating intracellular O2.- levels." (PMID 27391159, 2016). "Moreover, we indicated that introducing human cytoplasmic gelsolin cDNA suppresses tumorigenicity in human bladder and colon cancer cell lines." (PMID 12592377, 2003).
rheumatoid arthritis (14 papers, 2008 to 2026). A chronic, systemic autoimmune disorder characterized by inflammation in the synovial membranes and articular surfaces. "Within rheumatoid arthritis patients, reduced circulating levels of plasma gelsolin have been identified." (PMID 39972657, 2025). "The presence of actin and gelsolin-actin complexes in synovial fluids of rheumatoid arthritis patients corroborates the local consumption of the potentially anti-inflammatory gelsolin in the inflamed joint." (PMID 39090111, 2024). "Even during chronic conditions, such as rheumatoid arthritis and multiple sclerosis, plasma gelsolin levels were reduced." (PMID 39090111, 2024). "Based on its considerable expression decrease in pathologies characterized by a chronic inflammatory state such as arthritis rheumatoid, it has been postulated that GSN plays a protective role in inflammation." (PMID 36983904, 2023). "GSN is a multifunctional protein with altered blood levels in chronic inflammatory and autoimmune disorders such as rheumatoid arthritis, ankylosing spondylitis, systemic lupus erythematosus, and Henoch–Schoenlein purpura." (PMID 35453622, 2022). "Gelsolin was decreased in rheumatoid arthritis patients but increased in OA individuals, where it is considered a putative biomarker." (PMID 35228907, 2022). "Gelsolin can also be localized in the synovial membrane of patients with rheumatoid arthritis (RA) and osteoarthritis (OA)." (PMID 35327525, 2022). "Specific peptidic fragments were differentially excreted between groups; fragments of protein S100-A9 and gelsolin were less abundant in rheumatoid arthritis while fragments of uromodulin, complement C3 and fibrinogen were all increasingly excreted." (PMID 25144639, 2014). "On the other hand, we observed a decrease of GSN in blood and CSF, which agrees with a study showing that a decrease of blood gelsolin level is inversely related to the intensity of systemic inflammation in patients with rheumatoid arthritis (RA)." (PMID 21040581, 2010). "Circulating and intra-articular levels of plasma gelsolin were measured in 78 patients with rheumatoid arthritis using a functional (pyrene-actin nucleation) assay and compared with 62 age- and gender-matched healthy controls." (PMID 18822171, 2008). "Circulating plasma gelsolin levels were significantly lower in patients with rheumatoid arthritis compared with healthy controls (141 ± 32 versus 196 ± 40 mg/L, P = 0.0002)." (PMID 18822171, 2008). "The plasma isoform of gelsolin is decreased in the plasma of patients with rheumatoid arthritis compared with healthy controls." (PMID 18822171, 2008). "using a nano-LC-MS/MS-based proteomics approach speculated that SAA might be a biomarker of AA amyloidosis in rheumatoid arthritis; gelsolin and VDBP might be potent biomarker candidates for the early diagnosis of RA." (PMID 35603148, 2022). "In the present study, we investigated plasma gelsolin in patients with rheumatoid arthritis." (PMID 18822171, 2008). "Plasma gelsolin serves as a protective barrier to halt inflammatory responses within the body and has been observed to decrease during inflammatory arthritis, such as rheumatoid arthritis (RA)." (PMID 37908900, 2023).
lung cancer (12 papers, 2003 to 2025). A malignant neoplasm involving the lung. "GSN up‐regulation is associated with radio‐or chemoresistance in non‐small cell lung cancer and gynaecological cancer cells." (PMID 38803199, 2024). "To date, there has been a study that has identified GSN as a candidate gene significantly associated with the development of lung cancer in patients with a history of breast cancer, based on germline whole-exome sequencing (WES) of 28 cases." (PMID 37461096, 2023). "After controlling for age, stage, adjuvant chemotherapy, family history of lung cancer, and smoking history, the significant association remained between high levels of gelsolin and elevated risk of death (RR = 1.89, 95% CI = 1.17–3.05, p = 0.01)." (PMID 16882345, 2006). "We and others have showed that higher levels of gelsolin are associated with poorer survival in breast and lung cancer." (PMID 16882345, 2006). "A few other reports indicated the survival benefit of GSN under-expression in osteosarcoma and lung cancer." (PMID 37958747, 2023). "One study had performed WES on 28 of 60 patients from Italy with breast and lung cancer, and had identified one gene, GSN, to be significantly enriched." (PMID 37461096, 2023). "We found increased levels of CRP, SAA, α-1-antitrypsin (AAT) by two distinct antibodies, and MUC1, and decreased levels of transferrin and gelsolin, in lung cancer sera." (PMID 16117833, 2005). "We established stable clones of lung cancer cells overexpressing various levels of gelsolin to investigate the effects of gelsolin restoration on tumorigenicity." (PMID 12592377, 2003). "In this study, we demonstrated that gelsolin suppressed tumorigenicity of PC10 lung cancer cells through inhibiting a PKC signal transduction pathway." (PMID 12592377, 2003). "We previously demonstrated that expression of an actin-regulatory protein, gelsolin, is frequently downregulated in lung cancer and several types of different human cancers, such as stomach, bladder and colon." (PMID 12592377, 2003). "Gelsolin expression is frequently downregulated in lung cancer and several types of different human cancers." (PMID 12592377, 2003). "To examine the effects of gelsolin restoration on tumorigenicity, we here stably expressed various levels of gelsolin via gene transfer in lung cancer cells (squamous cell carcinoma line, PC10)." (PMID 12592377, 2003). "In studies of pancreatic and lung cancer, the precise role of GSN remains unclear due to evidence showing that GSN has a dual effect on tumor progression." (PMID 40597347, 2025). "In our studies, gelsolin-overexpressing lung cancer cells exhibited a significant growth inhibition under the low-level serum condition, consistent with our previous findings, decreased the ability of colony formation in soft agar and reduced tumorigenicity in nude mice." (PMID 12592377, 2003). "Recently, using 2D-DIGE, we identified several proteoforms of blood plasma proteins from lung cancer patients, including proapolipoprotein, apolipoprotein AIV, clusterin, gelsolin, fibrinogen, haptoglobin, hemopexin, transferrin, and serotransferrin." (PMID 35512017, 2022).
myocardial infarction (12 papers, 2010 to 2025). Gross necrosis of the myocardium, as a result of interruption of the blood supply to the area, as in coronary thrombosis. "For example, in a previous study, plasma gelsolin was shown to be downregulated in acute liver failure, myocardial infarction, septic shock, and myonecrosis." (PMID 30662913, 2018). "The expression levels of GSN in human heart tissues and mouse models were increased by different types of cardiac injuries, including pressure overload, acute myocardial infarction, dilated or ischemic cardiomyopathy, and end-stage heart failure." (PMID 30180843, 2018). "Gelsolin is known to have one of the key roles in extracellular actin-scavenger system (EASS), but the biological role of platelet gelsolin in platelet activation of acute myocardial infarction (AMI) is unclear." (PMID 23533533, 2013). "Gelsolin levels were significantly decreased in cardiovascular diseases and myocardial infarction." (PMID 40106086, 2025). "Gelsolin is the most abundant actin depolymerizing protein in plasma and its significantly depleted values have been reported in metabolic disorders including cardiovascular diseases and myocardial infarction." (PMID 31002695, 2019). "The biological role of platelet gelsolin in platelet activation of acute myocardial infarction is not defined." (PMID 23533533, 2013).
pancreatic cancer (12 papers, 2014 to 2023). "The diagnostic value of serum GSN protein alone for pancreatic cancer in diabetic patients was also good (AUC = 0.75)." (PMID 37035750, 2023). "In combination with lumican, gelsolin displays high accuracy in distinguishing pancreatic cancer from chronic pancreatitis (95% specificity)." (PMID 34947825, 2021). "Examples of consistent protein expression changes all the way up to clinical diagnosis of pancreatic cancer, were; gelsolin (GSN), apolipoprotein A4 (APOA4), coagulation factor 12 (F12) and lactotransferrin (LTF)." (PMID 24708694, 2014). "GSN is an actin-capping protein and GSN levels are actively downregulated in pancreatic cancer and the ubiquitin-proteasome pathway is an important contributing factor for this effect." (PMID 24708694, 2014). "Importantly, serum gelsolin, particularly together with lumican, was proposed as a highly sensitive combined biomarker for distinguishing pancreatic cancer and pancreatitis (at 95% specificity gelsolin-lumican reached 80% sensitivity)." (PMID 30149613, 2018). "Downregulation of gelsolin protein expression in most malignancies is attributes to gene inactivation mediated by epigenetic modifications or impairment of promoter activity regulated by activating transcription factors or by ubiquitin-proteasomal degradation, as reported in pancreatic cancer." (PMID 34947825, 2021). "Their results showed that gelsolin, lumican, and tissue inhibitor of metalloproteinase 1 have better area under curve (AUC) values than CA19-9 to discriminate pancreatic cancer from healthy controls and chronic pancreatitis controls." (PMID 33672926, 2021). "Three of the 5 candidate proteins, including GSN, lumican (LUM; a member of the SLRP family), and TIMP1, demonstrated an AUC value above 0.75 in differentiating pancreatic cancer from the controls." (PMID 24708694, 2014).
diabetes (11 papers, 2014 to 2025). "The multi-functional role of GSN and its systemic changes implicated in diabetes and PDAC warrant further investigation." (PMID 32545216, 2020). "In our model, we identified five differentially expressed diabetes-related genes, with GSN and PGR exhibiting heightened expression levels in the low-risk group, whereas CDKN2A, SELENOP, and TRPC1 demonstrated increased expression in the high-risk group." (PMID 41244925, 2025). "Our group also observed downregulated miR-21 in palmitate-treated CMs and db/db mice, which resulted in diabetes-induced diastolic dysfunction by increased gelsolin (GSN) levels and reduced NO production via Akt-eNOS-NO signaling." (PMID 33329700, 2020). "Further studies using gelsolin-null mice revealed a role for gelsolin in cancer development, pathogenesis of diabetes, neurodegenerative diseases, and involvement in osteoblast metabolism." (PMID 30149613, 2018). "The study aims to map plasma gelsolin (pGSN) levels in diabetic humans and mice models of type II diabetes and to evaluate the efficacy of gelsolin therapy in improvement of diabetes in mice." (PMID 25478578, 2014). "Depletion of pGSN led to the release of actin for tissue damage and cell death, and recombinant gelsolin might serve as a treatment for diabetes." (PMID 31384238, 2019). "Besides these diseases, exogenous administration of gelsolin has also shown protective effect in treatment of diabetes and stroke in mice and rats." (PMID 26426535, 2015). "Further experiments would provide a detailed insight into the mechanism(s) by which the glucose-gelsolin levels are related and whether and how monitoring pGSN values would improve diabetes care." (PMID 25478578, 2014). "To further validate the protein expression levels of the five key diabetes-related genes (CDKN2A, GSN, PGR, SELENOP, and TRPC1) identified in our prognostic model, we utilized IHC staining data from the HPA database." (PMID 41244925, 2025). "Our data indicated a strong correlation of plasma GSN and CLEC3B in plasma concentration of patients with diabetes." (PMID 32545216, 2020). "Our analysis revealed a distinct stratification: while TRPC1, SELENOP, CDKN2A, GSN, and PGR all showed significant dysregulation in UCEC tissues compared to normal endometrium, only SELENOP, CDKN2A, and PGR exhibited diabetes-specific modifications in UCEC patients." (PMID 41244925, 2025). "The prognosis of patients with AIS at 90-days after IVT was used as the dependent variable, and age, smoking, hypertension, diabetes, coronary artery disease, hyperlipidemia, atrial fibrillation, IL-6, MMP-9, ADAMTS13, TRX, TNC, and GSN were considered independent variables." (PMID 36127663, 2022). "In contrast, expression levels of TRPC1 and GSN remained comparable between diabetic and non-diabetic UCEC subgroups, indicating their involvement in general carcinogenesis rather than diabetes-specific pathways." (PMID 41244925, 2025).
hepatocellular carcinoma (11 papers, 2012 to 2025). A malignant tumor that arises from hepatocytes. "Conversely, GSN is upregulated in metastatic hepatocellular carcinoma tissues, promoting cell proliferation." (PMID 39964147, 2025). "In a different type of tumor, hepatocellular carcinoma, GSN has been shown to promote the proliferation of cells." (PMID 40597347, 2025). "Increased GSN expression level has been reported in breast, prostate, hepatocellular carcinoma and pancreatic cancers where it acts as an oncogene." (PMID 37958747, 2023). "On the other hand, B-cell lymphoma, GBM, acute myeloid leukemia glioma, hepatocellular carcinoma, prostate adenocarcinoma and thymoma exhibited significantly high levels of GSN compared to the expression levels in normal tissues." (PMID 37958747, 2023). "Liver has been suggested to be a major source of plasma gelsolin and human hepatoma cell line HepG2 produces and secretes plasma gelsolin." (PMID 22952982, 2012). "Here, we examined whether gelsolin can potentiate TRAIL mediated cell death in resistant human hepatoma cells." (PMID 28993697, 2017). "The biological function of GSN in hepatocellular carcinoma (HCC) and its mechanism remain unclear." (PMID 32377190, 2020). "In breast cancer and hepatocellular carcinoma (HCC), GSN promotes cell proliferation and metastasis." (PMID 35941115, 2022). "To evaluate the mechanisms of tumor resistance to TRAIL and the ability of gelsolin to sensitize cells to TRAIL mediated cell death, we investigated human hepatoma (HepG2) and hepatocellular carcinoma (Huh7) cells exhibiting reduced sensitivity to TRAIL19." (PMID 28993697, 2017).
prostate carcinoma (11 papers, 2015 to 2025). A carcinoma that arises from epithelial cells of the prostate gland. "A final notable member, actin-binding protein gelsolin (GSN), has been implicated in neuroendocrine transdifferentiation of prostate cancer." (PMID 39125581, 2024). "Gelsolin is associated with the invasion and metastasis of cancer cells, such as prostate cancer and lung adenocarcinoma." (PMID 30155403, 2018). "Gelsolin was highly expressed in prostate cancer cells, and was associated with tumor progression, recurrence, metastasis, and poor prognosis." (PMID 29100377, 2017). "In contrast, gelsolin is upregulated in prostate cancer, where it promotes progression and metastasis." (PMID 41006687, 2025). "Here, we demonstrate that gelsolin, a constituent of ejaculate, induces apoptosis of activated lymphocytes in prostate cancer." (PMID 29100377, 2017). "Although gelsolin is considered as a tumor suppressor in many types of malignancies, e.g., breast, bladder, colon, gastric, kidney, lung, oral, ovarian, pancreatic, and prostate cancers (reviewed by Li with colleagues), there is very little known about gelsolin in CNS and PNS tumors." (PMID 25352156, 2016). "Moreover, several reports point toward involvement of gelsolin in various human cancers, due to the observation that GSN expression was downregulated in numerous types of cancers, e.g., breast, bladder, colon, gastric, kidney, lung, oral, ovarian, pancreatic, and prostate cancer." (PMID 25352156, 2016). "Importantly for six of the eight candidates, (TRIB1, PCA3, GRHL2, ACTG2, GSN, and MXI1) we were able to confirm the differential expression of the genes that harbor these STRs using a large dataset of prostate cancers compared to adjacent non-malignant cells." (PMID 29203868, 2017).